ARHGAP45 (Rho GTPase activating protein 45)
Description:
Contains a GTPase activator for the Rho-type GTPases (RhoGAP) domain that would be able to negatively regulate the actin cytoskeleton as well as cell spreading. However, also contains N-terminally a BAR-domin which is able to play an autoinhibitory effect on this RhoGAP activity. Precursor of the histocompatibility antigen HA-1. More generally, minor histocompatibility antigens (mHags) refer to immunogenic peptide which, when complexed with MHC, can generate an immune response after recognition by specific T-cells. The peptides are derived from polymorphic intracellular proteins, which are cleaved by normal pathways of antigen processing. The binding of these peptides to MHC class I or class II molecules and its expression on the cell surface can stimulate T-cell responses and thereby trigger graft rejection or graft-versus-host disease (GVHD) after hematopoietic stem cell transplantation from HLA-identical sibling donor. GVHD is a frequent complication after bone marrow transplantation (BMT), due to mismatch of minor histocompatibility antigen in HLA-matched sibling marrow transplants. Specifically, mismatching for mHag HA-1 which is recognized as immunodominant, is shown to be associated with the development of severe GVHD after HLA-identical BMT. HA-1 is presented to the cell surface by MHC class I HLA-A*0201, but also by other HLA-A alleles. This complex specifically elicits donor-cytotoxic T-lymphocyte (CTL) reactivity against hematologic malignancies after treatment by HLA-identical allogenic BMT. It induces cell recognition and lysis by CTL.
Synonyms: HMHA1; KIAA0223; HA-1; HLA-HA1
Tractability: Antibody: its Gene Ontology location is reachable by antibodies, with high confidence; the Human Protein Atlas places it where antibodies can reach. PROTAC: ubiquitination databases record sites on it.
Gene: Protein-coding gene on chromosome 19 (1,065,923 to 1,086,642, forward strand). Ensembl gene ENSG00000180448.
Subcellular location: Cytoplasm; Cell projection, ruffle membrane
Subcellular location (Human Protein Atlas): Cytosol; Plasma membrane
Pathways (Reactome):
Signal Transduction: CDC42 GTPase cycle; RAC1 GTPase cycle; RHOA GTPase cycle
Immune System: Neutrophil degranulation
Gene Ontology:
Molecular function: protein binding; GTPase activator activity
Biological process: negative regulation of small GTPase mediated signal transduction; regulation of small GTPase mediated signal transduction; signal transduction
Cellular component: cytoplasm; cytosol; membrane; plasma membrane; azurophil granule lumen; extracellular region; secretory granule lumen; ruffle membrane
Genetic constraint (gnomAD): Loss-of-function variants: 58 observed, 96.28 expected, observed/expected ratio (o/e) 0.6, 90% interval 0.49 to 0.75. The synonymous counts are far from expectation, so gnomAD's model fits this gene poorly and the ratio says little. Missense variants: 1,621 observed, 1,489.6 expected, observed/expected ratio (o/e) 1.09, 90% interval 1.04 to 1.13. Synonymous variants: 866 observed, 663.31 expected, observed/expected ratio (o/e) 1.31, 90% interval 1.23 to 1.38.
Homologues: Orthologues: chimpanzee ARHGAP45 (97% identical), macaque ARHGAP45 (95% identical), pig ARHGAP45 (82% identical), rat Arhgap45 (80% identical), mouse Arhgap45 (80% identical), dog ARHGAP45 (78% identical), tropical clawed frog arhgap45 (57% identical), zebrafish arhgap45b (53% identical), zebrafish arhgap45a (51% identical), Caenorhabditis elegans spv-1 (19% identical), zebrafish arhgap45b (12% identical). Paralogues in human: ARHGAP29 (32% identical), GMIP (26% identical).
Diseases named in the same sentence as ARHGAP45 in open-access papers:
ARHGAP45 is named in the same sentence as 9 diseases in open-access papers, as found by Europe PMC text mining. Sharing a sentence is not in itself a finding about the gene and the disease. The quoted sentences say what the papers report.
lymphopenia (1 paper, 2021). Reduction in the number of lymphocytes. "It suggests that the T‐cell lymphopenia observed in Arhgap45−/− mice does not result from the presence of slightly diminished SP numbers but is rather due to the reduced ability of Arhgap45−/− T cells to enter into LNs and receive enough survival‐promoting signals on fibroblastic reticular cells." (PMID 33719206, 2021).
tumor (7 papers, 2013 to 2024). "ARHGAP45 plays a pivotal role in regulating tumor cell migration and invasion, processes integral to cancer metastasis." (PMID 39439803, 2024). "For example, by specifically identifying and targeting ARHGAP45-expressing tumor cells, TCR-T cells can directly attack these highly migratory and invasive cancer cells, thereby reducing the risk of metastasis and improving overall therapeutic outcomes." (PMID 39439803, 2024). "In the context of TCR-T cell therapy, targeting ARHGAP45 may help to inhibit tumor invasiveness and metastatic potential." (PMID 39439803, 2024). "For instance, ARHGAP45 inhibition could enhance the effects of other immunotherapies such as immune checkpoint inhibitors, by improving the immune system’s ability to recognize and destroy tumors by reducing the invasiveness of tumor cells." (PMID 39439803, 2024). "Additionally, targeting ARHGAP45 may work synergistically with other anti-tumor therapies." (PMID 39439803, 2024).
cancer (6 papers, 2013 to 2024). A tumor composed of atypical neoplastic, often pleomorphic cells that invade other tissues. "In the present study, we demonstrated that human minor histocompatibility antigen 1 (HMHA1; also known as ARHGAP45) is induced under hypoxic conditions in a HIF-dependent manner, and is responsible for the augmented invasion activity of hypoxic cancer cells." (PMID 38740970, 2024).
ARHGAP45 also shares sentences with these, for which no sentence is quoted: acute myeloid leukemia (1 paper); anaemia (1); hematological malignancies (1); leukemia (1); liver diseases (1); preeclampsia (1).